ALDOC (aldolase, fructose-bisphosphate C)
Diseases named in the same sentence as ALDOC in open-access papers (continued):
Sharing a sentence is not in itself a finding about the gene and the disease.
tumor (continued). "In particular, we observed that 3D tumor spheroid growth implies the overexpression of ALDOC and ENO2 glycolytic enzymes concomitant with the enhanced consumption of glucose and fructose and the enhanced production of lactate." (PMID 36945054, 2023). "Meanwhile, ALDOC positively regulates the Wnt pathway, which is involved in tumor development, by blocking the GSK-3β-axin interaction and targeting axin to a Dvl-induced signalosome." (PMID 34838074, 2021). "Among the identified genes, ALDOB was associated with a low risk, while five genes (GPC1, ALDOC, ENO2, SERPINE1, and SLC2A3) were associated with a high risk of developing tumor malignancy." (PMID 33737938, 2021). "Compared with solid normal tissue, significantly lower ALDOC expression was detected in recurrence tumor (p = 0.0001)." (PMID 31450822, 2019). "Increased ALDOB and ALDOC expression can lead to Wnt-signaling pathway activation in tumor cells, which contributes to disease progression." (PMID 30967137, 2019). "Through TCGA data set mining, we further compared the expression level of ALDOC between the recurrent tumor site and its counterpart from the same patient (primary site)." (PMID 31450822, 2019). "ALDOC's involvement in cancer is paradoxical, contributing to both tumor proliferation and suppression, underscoring how shifts in the tumor microenvironment (e.g., nutrient availability, hypoxia, or lactate accumulation) can toggle ALDOC's function between pro-tumor and anti-tumor states." (PMID 40520908, 2025). "Moreover, in vivo studies using xenograft models confirmed that ALDOC knockdown attenuated tumor growth." (PMID 40518543, 2025). "The regulation of metabolic-related genes, such as SLC25A22, may reverse radiotherapy resistance, while PPAR-γ agonists can inhibit tumor progression by regulating the ALDOC-PPAR-γ axis." (PMID 41201287, 2025). "Moreover, it was also demonstrated that ALDOC expression increases significantly along with the elevation of the malignancy of tumor, such as more advanced T stage, N stage, pathological stage, and more serious lymph node invasion." (PMID 40518543, 2025). "In several tumor types, ALDOC expression is related to poor clinical outcome." (PMID 38238671, 2024). "The increased intracellular ratio L-lactic acid/Glucose monophosphate and D-Fructose monophosphate in all 3D tumor spheroids compared to their relative 2D cultures well agreed with the up-regulation of the glycolytic enzymes ALDOC and ENO2, at both gene and protein levels." (PMID 36945054, 2023). "In this study, we also examined whether ALDOC expression presented in tumor blood vessels and perinecrotic areas." (PMID 31450822, 2019). "In the future, a newly-developed, targeted activator of ALDOC might be a potential effector to slow down tumor progression after verification." (PMID 31450822, 2019). "Furthermore, the detection of ALDOC expression was performed in solid tissue of normal, primary tumor, and recurrence tumor groups." (PMID 31450822, 2019). "The observation indicates that ALDOC may be the tumor suppressor gene, and is activated when one or more tumor suppressor genes are blocked in chromosome 1p/19q regions." (PMID 31450822, 2019). "Therefore, low ALDOC expression and advanced tumor grade were significantly correlated with unfavorable overall survival." (PMID 31450822, 2019). "Several studies have indicated that ALDOB and ALDOC could suppress tumor invasive and metastatic potential in hepatocellular and oral squamous carcinomas." (PMID 31450822, 2019). "Accordingly, over-expression of ALDOA and ALDOC were previously reported in various tumor types." (PMID 24993527, 2014). "Therefore, we utilized proteomics/phosphoproteomics to claim whether ALDOC is a tumor suppressor in GBM." (PMID 31450822, 2019).
tumor (continued). "In terms of regulating the tumor immune microenvironment, the discovery of the ALDOC-PPAR-γ axis has opened up new avenues for targeted therapy, with PPAR-γ agonists exerting anti-tumor effects by regulating metabolic and inflammatory response pathways." (PMID 41201287, 2025). "It was found that enhancement of glycolysis reduced the sensitivity of tumor cells to L-OHP, while hypoxia enhanced the glycolysis of tumor cells by regulating the expression of ALDOC." (PMID 40535800, 2025). "HE, IHC staining and WB showed the expression of MAT1A, CCND1, proliferation marker Ki67 and glycolytic marker (ALDOC, HK2) in tumor tissues, emphasizing the regulation of MAT1A and CCND1 on NSCLC cells." (PMID 39438468, 2024). "Taken together, these data revealed that BRD9 activates transcriptions of ALDOC and ENO2 to enhance glycolytic metabolism and tumor progression in COAD." (PMID 35778964, 2023). "The expression of differential genes related to PPP, including TKT, TKTL1, PGM1, GPI, FBP2, ALDOA and ALDOC, were all upregulated in WDLPS tumor samples, which were validated by Real-time Quantitative PCR (RT-qPCR)." (PMID 36557266, 2022). "Besides, we provided evidence that expression level of ALDOC may link to tumor grade." (PMID 31450822, 2019). "The proteomic clusters included tumor upregulated (PRDX3, APOA1, CLIC1) and downregulated (NFM, NDUS1, MDHC, ALDOC, STMN1, PEBP1, DDAH1, CN37) proteins." (PMID 25050814, 2014). "While the upregulation of DKK3 and ALDOC enhanced differentiation, the downregulation of ID1 may reduce the oncogenic potential, reinforcing the tumor-suppressive effects of the treatment." (PMID 40753072, 2025). "Additionally, the results indicated a significant decrease in serotonin and related molecules, accompanied by the restoration of ALDOC and NR2F1 expression, in addition to the inhibition of tumor growth." (PMID 38741139, 2024). "In this study, immunohistochemistry was used to analyze the expression of aldolase, fructose-bisphosphate C (ALDOC) protein in tumor tissues and adjacent non-malignant tissues from 79 NSCLC patients." (PMID 37724906, 2023). "The results indicated that ALDOC expression was significantly increased in tumor tissues; not only that, ALDOC expression was higher in metastatic NSCLC as compared to earlier stages (P < 0.001)." (PMID 37724906, 2023). "In addition, tumor cells need to increase their efficiency by increasing glucose transporters, or various key enzymes, such as hexokinase 2 (HK2), pyruvate kinase M2 (PKM2), lactate dehydrogenase A (LDHA), aldolase C (ALDOC), alcohol dehydrogenase gene (ADH6)." (PMID 39438468, 2024). "However, ALDOC does not universally promote tumor development." (PMID 40520908, 2025).
cancer (27 papers, 2014 to 2025). A tumor composed of atypical neoplastic, often pleomorphic cells that invade other tissues. "Among these genes, we focused our attention on UBE2N due to its significant association with ALDOC and its known involvement in the development of various human cancers." (PMID 37724906, 2023). "Previous studies have shown that the ALDOC is a member of the aldolase family and has been identified as an independent prognostic hallmark for cancers." (PMID 35922788, 2022). "Their study demonstrated that the inhibition of EPB41 expression in cancer cells increased the levels of ALDOC protein released from the EPB41-ALDOC complex." (PMID 38397451, 2024). "The altered expression of ALDOC has been linked to various metabolic pathways, including glycolysis and pentose phosphate pathway (PPP) metabolism, in cancer cells." (PMID 37724906, 2023). "ALDOC was identified as activators of Wnt signaling, a signaling pathway involved in cancer genesis and progression when it was over-activated." (PMID 34777463, 2021). "ALDOC exhibits a complex duality in its role across various cancer types." (PMID 40520908, 2025). "The roles of ALDOB or ALDOC vary across different cancer types." (PMID 38741139, 2024). "The knockdown of ALDOC reduces cell growth, glucose uptake, and glycolysis in cancer cells." (PMID 36845730, 2023). "As previously discussed, both ALDOC and PGK1 are glycolysis-related proteins known to significantly regulate aerobic glycolysis in malignant tumors." (PMID 40518543, 2025). "GBM tumors displayed distinct Warburg-like genetic features, with increased HK2, PGAM1, ALDOC, and PGK1 expression that facilitates lactate production and confers resistance to hypoxic stress in cancer cells." (PMID 35004842, 2021). "Interestingly, during our exploration of downstream of ALDOC, its co-expression feather with PGK1, another key enzyme in glycolysis as well as in cancer development, brings our eyes back to the relevant field of glycolysis." (PMID 40518543, 2025). "While ALDOC is a crucial enzyme in glycolysis, many studies also showed its contribution in cell proliferation, cell morphology regulation and cancer progression in non-glycolytic pathways." (PMID 39527598, 2024). "Future in vivo studies will be necessary to assess the role of ALDOC and ENO2 in cancer metastasis." (PMID 36945054, 2023). "Expression of 2 genes coding for metabolic enzymes (ALDOC, ETNPPL) was modified suggesting that foci might have an altered metabolism as often observed during cancer progression." (PMID 32218467, 2020). "After the correlation between the ALDOC methylation status and RNA expression level was analyzed in GBM cell lines, a significant negative correlation was found in GBM cell lines according to the Cancer Cell Line Encyclopedia (CCLE) (Spearman’s rho = -0.774, pvalue = 7.7e-09)." (PMID 38741139, 2024). "Additionally, ALDOC can be involved in nonglycolytic roles and in cancer progression." (PMID 33274599, 2021).
infection (8 papers, 2011 to 2024). The state of being infected such as from the introduction of a foreign agent such as serum, vaccine, antigenic substance or organism. "HiRIEF LC-MS/MS detected alterations in the remaining proteins, i.e., ISG20, PSMB8, PSMB10, ALDOC, and SERPINB1, emphasising the method’s ability to capture alterations deriving from infection that are not picked up by other methods." (PMID 37739942, 2023). "Amongst genes regulated by infection with acidosis but not at pH 7.4 the Reactome gene set “glycolysis” was enriched and expression of glycolysis genes (HK2, ALDOC, LDHB) was increased by acidosis." (PMID 37418488, 2023).
psychiatric disorder (3 papers, 2013 to 2021). A disorder characterized by behavioral and/or psychological abnormalities, often accompanied by physical symptoms. "The differentially expressed proteins included those previously implicated in psychiatric disorders, such as ALDOC, ENO1, and PRDX2." (PMID 23408933, 2013). "Among the proteins identified, both ALDOC and ENO1 have been previously associated with psychiatric disorders." (PMID 34576123, 2021).
bacterial infection (1 paper, 2022). "In summary, pathogenic bacterial infection upregulated PKM, LDHB, LDHA, ALDOA, PGD, GPI, and ALDOC, increased ATP production, which promotes leukocyte recruitment and NALP3-inflammasome activation, increases NADPH production, and promotes ROIs modulating inflammation and injury." (PMID 36335251, 2022).
ALDOC also shares sentences with these, for which no sentence is quoted: depression (2 papers); meningioma (2); neuroblastoma (2); non-small cell lung carcinoma (2); Alzheimer disease (1); benign prostatic hyperplasia (1); colon adenocarcinoma (1); low grade glioma (1); lung adenocarcinoma (1); Lymphatic Metastasis (1); lymphoma (1); mental disorder (1); metastatic melanoma (1); myelogenous leukemia (1); neurodevelopmental disorder (1); oligodendroglioma (1); rectal adenocarcinoma (1); sarcopenia (1); Sepsis (1); type II diabetes (1); viral infection (1).